GAB1 (GRB2 associated binding protein 1)
Description:
Adapter protein that plays a role in intracellular signaling cascades triggered by activated receptor-type kinases. Plays a role in FGFR1 signaling. Probably involved in signaling by the epidermal growth factor receptor (EGFR) and the insulin receptor (INSR). Involved in the MET/HGF-signaling pathway.
Synonyms: DFNB26
Tractability: Small molecule: a high-quality ligand is known. Antibody: the Human Protein Atlas places it where antibodies can reach. PROTAC: ubiquitination databases record sites on it; its protein half-life has been measured; a small molecule that binds it is known.
Gene: Protein-coding gene on chromosome 4 (143,336,402 to 143,474,565, forward strand). Ensembl gene ENSG00000109458.
Subcellular location (Human Protein Atlas): Plasma membrane; Nucleoli fibrillar center
Pathways (Reactome):
Signal Transduction: Activated NTRK2 signals through PI3K; Erythropoietin activates Phosphoinositide-3-kinase (PI3K); GAB1 signalosome; MET activates PI3K/AKT signaling; MET activates PTPN11; MET activates RAP1 and RAC1; MET receptor recycling; PI-3K cascade:FGFR1; PI-3K cascade:FGFR2; PI-3K cascade:FGFR3; PI-3K cascade:FGFR4; PI3K Cascade; PI3K events in ERBB2 signaling; PI5P, PP2A and IER3 Regulate PI3K/AKT Signaling; PIP3 activates AKT signaling
Disease: Constitutive Signaling by Aberrant PI3K in Cancer; Constitutive Signaling by EGFRvIII; Constitutive Signaling by Ligand-Responsive EGFR Cancer Variants; Signaling by ERBB2 ECD mutants; Signaling by ERBB2 KD Mutants; Signaling by FGFR1 in disease; Signaling by FGFR2 in disease; Signaling by FGFR3 in disease; Signaling by FGFR4 in disease
Developmental Biology: RET signaling
Gene Ontology:
Molecular function: protein binding; signaling adaptor activity
Biological process: angiogenesis; endothelial cell chemotaxis; positive regulation of angiogenesis; vascular endothelial growth factor signaling pathway; cellular response to mechanical stimulus; epidermal growth factor receptor signaling pathway; insulin receptor signaling pathway; intracellular signal transduction; positive regulation of blood vessel endothelial cell migration; positive regulation of phosphatidylinositol 3-kinase/protein kinase B signal transduction; signal transduction; vasodilation; cellular response to vascular endothelial growth factor stimulus
Cellular component: cell-cell junction; cytoplasm; cytosol; cell cortex
Genetic constraint (gnomAD): Loss-of-function variants: 19 observed, 55.45 expected, observed/expected ratio (o/e) 0.34, 90% interval 0.24 to 0.5. The upper end of that interval is the gene's LOEUF score, 0.5, which puts it in group 2 of 6, group 1 being the genes least tolerant of losing a copy. Missense variants: 670 observed, 818.55 expected, observed/expected ratio (o/e) 0.82, 90% interval 0.77 to 0.87. Synonymous variants: 272 observed, 290.3 expected, observed/expected ratio (o/e) 0.94, 90% interval 0.85 to 1.04.
Homologues: Orthologues: chimpanzee GAB1 (99% identical), macaque GAB1 (99% identical), pig GAB1 (94% identical), rabbit GAB1 (94% identical), guinea pig GAB1 (94% identical), mouse Gab1 (90% identical), rat Gab1 (89% identical), tropical clawed frog gab1 (75% identical), zebrafish gab1 (65% identical), Drosophila melanogaster dos (21% identical), Caenorhabditis elegans soc-1 (14% identical). Paralogues in human: GAB2 (40% identical), GAB3 (28% identical), GAB4 (24% identical), PHLDB1 (19% identical), PHLDB2 (15% identical), PLEKHS1 (11% identical), PHLDB3 (7% identical).
Diseases named in the same sentence as GAB1 in open-access papers:
GAB1 is named in the same sentence as 105 diseases in open-access papers, as found by Europe PMC text mining. Sharing a sentence is not in itself a finding about the gene and the disease. The quoted sentences say what the papers report.
breast cancer (19 papers, 2009 to 2025). A primary or metastatic malignant neoplasm involving the breast. "Previous work has also indicated a positive link between ROK/Gab-1 associated PI3K/AKT signalling activation during HA/CD44-mediated breast cancer progression." (PMID 37707669, 2023). "In breast cancer, GAB1 cancer-associated mutations, Y83C and T387N, have been described and characterized." (PMID 37627207, 2023). "Expression of Gab1 is associated with many cancer, such as ovarian cancer, breast cancer, chondrosarcoma, colorectal cancer, urothelial cell carcinoma and so on." (PMID 29212272, 2017). "GAB1 is associated with tamoxifen resistance in metastatic breast cancer patients." (PMID 37627207, 2023). "GAB1 germline copy number variation is linked to breast cancer risk." (PMID 37627207, 2023). "The effects of SHP2 GOF mutations on breast cancer cells might occur though the Gab1-ERK signalling axis." (PMID 26673822, 2016). "EGF induced the associations of Gi3α with p-EGFR, Gab1 and Shp2 in breast cancer cells." (PMID 24521094, 2014). "In vitro, elevated GAB1 expression has been reported to enhance the migration of MDA-MB231 and SK-BR3 breast cancer cells through dissociation of the polarity-associated partitioning defective (PAR) complex." (PMID 37627207, 2023). "GAB1 has been proven as a pro-cancer factor to promote proliferation in glioma, cell metastasis in breast cancer, and proliferation and invasion in non-small cell lung cancer." (PMID 34287578, 2021). "Further research should focus on identification of a therapeutic target in the Gab1-ERK signalling pathways to inhibit the development of breast cancer and exploration of novel preventative and treatment strategies for this disease." (PMID 26673822, 2016). "This effort represents the discovery of first-in-class GAB1 PH domain inhibitors with potential for targeted breast cancer therapy and provides novel insights into structure-based approaches to targeting this protein." (PMID 25569504, 2015). "With our integrated protocol, we have successfully identified several selective inhibitors targeting the GAB1 PH domain and they are selective to breast cancer cells." (PMID 25569504, 2015). "Upon biological evaluation, five out of the initially tested 20 hits exhibited positive activities to form direct binding to GAB1 PH domain, inhibit GAB1 Y627 phosphorylation and suppress breast cancer cell proliferation with low micromolar IC50." (PMID 25569504, 2015). "The Giα proteins associated with RTKs, Gab1, FRS2 and Shp2 in breast cancer cells and their ablation impaired Gab1’s interactions with Shp2 in response to EGF and IGF-1, or with FRS2 and Grb2 in response to bFGF." (PMID 24521094, 2014). "The interaction of CD44 and HA activates RhoA signals and Rho kinase, enhances serine/threonine phosphorylation on Gab-1 (Grb2-associated binder-1), induces PI3K activation, triggers the PI3K/Akt pathway, and is involved in the progression of breast cancer." (PMID 21294926, 2011). "GAB1 expression appears to be deregulated in a wide variety of tumors such as thyroid cancer, cervical cancer, breast cancer, meningiomas, cholangiocarcinoma, medulloblastomas, chronic lymphocytic leukemia, head and neck cancer, and colorectal cancer, among others." (PMID 37627207, 2023). "Furthermore, in breast cancer, GAB1 overexpression has been described to promote metastasis in vivo by PAR complex dissociation." (PMID 37627207, 2023). "Furthermore, research indicates that upregulating Gab1 increases breast cancer (BCs) and metastasis by separating the PAR complex, which has been identified as a major regulator of EMT." (PMID 36644780, 2023). "A correlation between the tyrosine phosphorylation status of Gab1 and the progression of ErbB2-transgene driven murine mammary tumours has also been reported, indicating that Gab1 needs to be considered as an important downstream effector of this oncogenic RTK as well." (PMID 19737390, 2009).
breast cancer (continued). "Therefore, inhibition of GAB1 PH domain functions may prevent the recruitment of GAB1 to the membrane and suppress cancer cell (e.g., breast cancer) proliferation and metastasis." (PMID 25569504, 2015). "GAB1 is involved in MET-mediated radiotherapy resistance mechanisms, promoting invasive growth in breast cancer, melanoma, and glioblastoma cell lines." (PMID 37627207, 2023). "We report that TME lactate triggers the assembly of the lactate receptor hydroxycarboxylic acid receptor 1 (HCAR1)-associated protein complex, which includes GRB2, SOS1, KRAS, GAB1, and PI3K, for the activation of both the RAS and the PI3K oncogenic signaling pathways in breast cancer (BCa) cells." (PMID 39199589, 2024). "To validate our in silico identified hits, we performed three types of experimental assays to evaluate their bioactivities: direct binding to GAB1 PH domain, inhibition of Y627 phosphorylation of GAB1, and cytotoxicity IC50 in triple negative MDA-MB-231 and T47D human breast cancer cells." (PMID 25569504, 2015). "Moreover, these hits inhibited the phosphorylation of GAB1 and demonstrated potent, tumor-specific cytotoxicity against MDA-MB-231 and T47D breast cancer cell lines." (PMID 25569504, 2015). "Indeed, such a scenario is supported by experiments in which the expression of the isolated PH domain of Gab1 suppressed EGF-induced ERK and AKT activation in breast cancer cell lines." (PMID 19737390, 2009). "Of note, all GAB1-selective or IRS1-selective inhibitors showed much better IC50 against T47D and MDA-MB-231 breast cancer cell lines than the non-tumorigenic MCF-10A cell line." (PMID 25569504, 2015). "This may imply that targeting GAB1 or IRS1, but not AKT1, might be a better targeted strategy for breast cancer treatment." (PMID 25569504, 2015).
hepatocellular carcinoma (12 papers, 2013 to 2024). A malignant tumor that arises from hepatocytes. "On the other hand, GAB1 (Grb2-associated binding protein 1) has high-level expression in hepatocellular carcinoma tissue and is determined as a miR-150 target." (PMID 37924077, 2023). "Association of GRB2 and GAB1 expression with clinicopathological features of 130 hepatocellular carcinoma patients." (PMID 24391994, 2013). "Interestingly, high levels of GAB1 expression are associated with poor prognosis in patients with gliomas, hepatocellular carcinoma, and ovarian cancer." (PMID 37627207, 2023). "Although Grb2-associated binding protein 1 (Gab1) has been implicated in tumor proliferation and metastasis in multiple tumors including colorectal cancer, hepatocellular carcinoma and ovarian cancer, whether and how it regulates BCa metastasis are still poorly understood." (PMID 30665442, 2019). "Gab1 knockdown in mouse hepatoma cells treated with CCL4 alone, or CCL4 plus HGF, showed a significant increase in cleaved caspase-3, along with decreased pERK1/2 and pSTAT3, as compared to control cells." (PMID 38935609, 2024). "In Gab1 knockdown hepatoma cells, cell proliferative signaling activity was reduced but the level of activated caspase-3 was increased." (PMID 38935609, 2024). "Hepatoma cells showed elevation of p-Gab1, along with an increase in STAT3 and ERK activation, upon treatment with HGF (ligand of HGF receptor/c-Met) and CCL4." (PMID 38935609, 2024). "GAB1 downregulation reduced migratory and invasive capacity in hepatocellular carcinoma, hilar cholangiocarcinoma, oral squamous cell carcinoma, and colorectal carcinoma cell lines." (PMID 37627207, 2023). "In hepatocellular carcinoma cell lines, GAB1 knockdown inhibited cell proliferation by reducing of ERK1/2 activation." (PMID 37627207, 2023). "GAB1 was found to be directly targeted by hsa-miR-200a, a miRNA family including hsa-miR-429, to suppress cell invasion and migration of hepatocellular carcinoma." (PMID 37533517, 2022). "In hepatocellular carcinoma, miR-150 is downregulated, and miR-150 weakened cell viability, colony formation, migration, and invasion by regulating the GAB1/ERK axis." (PMID 33817286, 2020). "In agreement with our findings, repression of Gab1 expression has been previously shown to inhibit metastasis in multiple cancers including colorectal cancer, hepatocellular carcinoma, ovarian cancer and hilar cholangiocarcinoma." (PMID 30665442, 2019). "According to previous research, in hepatocellular carcinoma, miR-150 suppresses cell proliferation and metastasis by inhibiting the GAB1-ERK axis." (PMID 27903978, 2017). "For instance, Morrbid binds to the promoter of PIK3CA in the nucleus to enhance its transcription and interacts with miR-150 to upregulate GRB2-associated binder 1 (GAB1) expression, which increases the phosphorylation of ERK1/2 and AKT in hepatocellular carcinoma." (PMID 39263145, 2024). "Interestingly, kinetic studies for the expression of Gab1 in infected hepatoma cells revealed an inverse relationship between Gab1 and TGF-β synthesis." (PMID 38935609, 2024). "Quercetin treatment (80 μM) also suppressed the phosphorylation of c-Met and its downstream effectors including Gab1 (GRB2-associated-binding protein 1), FAK and PAK (p21-activated kinases) in the human medulloblastoma cell line DAOY, human hepatoma HepG2 and melanoma A375 and A2058 cell lines." (PMID 38540096, 2024). "To test this, we determined Gab1 expression following co-treatment with CCL4 and HGF using the mouse hepatoma cell line Hepa1-6 cells." (PMID 38935609, 2024). "It suggests that Gab1 activation may play a role in regulation of TGF-β synthesis and production under the condition of acute viral infection in hepatoma cells." (PMID 38935609, 2024).
lung carcinoma (11 papers, 2009 to 2023). "Overexpression of Grb2-associated binding protein 1 (GAB1) has been observed in several human cancers, such as breast and lung cancers." (PMID 25569504, 2015). "The current study presents the novel findings that the scaffolding protein, Grb2-associated-binding protein 1 (Gab-1), regulates opioid and growth factor-mediated human lung cancer cell proliferation, migration and EMT transformation." (PMID 24662916, 2014). "Moreover, GAB1 is associated with HGF-stimulated VEGF production in EGFR-mutant lung cancer cell lines." (PMID 37627207, 2023). "Furthermore, genetic polymorphisms in GAB1 have been reported to increase susceptibility to developing some types of cancer, such as cholangiocarcinoma, meningiomas, and lung cancer." (PMID 37627207, 2023). "It has been reported that rs1397529 in GAB1 is negatively associated with the risk of lung cancer, and could serve as a novel biomarker for lung cancer." (PMID 31892308, 2019). "Our study might demonstrate that rs1347093 in MIR217HG and rs1397529 in Gab1 could be meaningful as the novel biomarker for lung cancer risk." (PMID 29212272, 2017). "GAB1 has been established to participate in HGF-induced resistance to cetuximab in lung cancer cell lines both in vitro and in vivo by promoting cell survival through AKT activation." (PMID 37627207, 2023). "(GAB1), which were reported to be involved in the progression of lung cancer, were identified as potential targets of miR-326." (PMID 32493389, 2020). "On the other hand, we demonstrated that in AXL-low-expressing EGFR-mutated lung cancer cells, osimertinib exposure increased protein expression and phosphorylation of IGF-1R and thereby restored the survival signal mainly via Gab1 and IRS1 to emerge tolerant." (PMID 32929081, 2020). "In addition, the opioid receptor Mu has been illustrated to promote EGF-induced migration and mesenchymal epithelial–mesenchymal transition through GAB1 recruitment in the lung cancer cell line H358." (PMID 37627207, 2023). "Also, GAB1 has been suggested to be a novel ideal target for controlling epidermal growth factor receptor mutant lung cancer." (PMID 31892308, 2019). "Indeed, in one study, exogenous HGF induced resistance to an anti-EGFR antibody in lung cancer cells (via the Met/Gab1/Akt signaling pathway)." (PMID 28619066, 2017). "Furthermore, a recent study has revealed Gab1 not only as a convergence point between c-MET and EGFR pathways, but also suggests that Gab1 cooperates with MET amplification in lung cancer cells, which have become resistant towards the EGFR inhibitor gefitinib." (PMID 19737390, 2009). "Together with findings that osimertinib increased the IGF-1R protein level, these results strongly suggest that an increased amount of IGF-1R, which maintains the association with EGFR and Gab1, may restore survival signals in AXL-low-expressing EGFR-mutated lung cancer cells exposed to osimertinib." (PMID 32929081, 2020). "GAB1 has been depicted as participating in the mechanism of HGF-induced EGFR-tyrosine kinase inhibitors (TKIs, osimertinib and gefitinib) resistance in lung cancer cell lines." (PMID 37627207, 2023). "These events induce recruitment of the scaffolding protein, Gab1, to the plasma membrane and consequent recruitment/activation of PI3 kinase, Akt and STAT3 signaling which are required for human lung cancer proliferation, migration and EMT." (PMID 24662916, 2014). "We previously reported that HGF activates the MET/GAB1 pathway and increases VEGF production by EGFR mutant lung cancer cells." (PMID 23690929, 2013). "In addition, inhibiting MOR attenuates growth factor-induced phosphorylation/activation of Src, Gab-1, PI3 kinase, Akt and STAT3 with consequent inhibition of human lung cancer proliferation, migration and EMT." (PMID 24662916, 2014).
medulloblastoma (11 papers, 2016 to 2024). A malignant, invasive embryonal neoplasm arising from the cerebellum. "It has been delineated that GAB1 is a biomarker of poor prognosis in meningiomas, medulloblastomas, and bone and soft tissue sarcomas." (PMID 37627207, 2023). "In primary medulloblastoma tissues, these groups are thought to be distinguishable using the immunohistochemical detection of β-catenin, filamin A, GAB1 and YAP1 protein markers." (PMID 28231263, 2017). "GAB1 immunostain was validated at AKUH at the conclusion of the study and is now routinely performed to enable identification of SHH-activated subtype of medulloblastoma." (PMID 38764578, 2024). "They subsequently performed immunohistochemistry for GAB1, which yielded a focal staining pattern that confirmed secondary SHH pathway activation, reflecting intratumoural heterogeneity within these WNT medulloblastomas." (PMID 33172502, 2020). "In this study, we investigated the possibilities of using the intracellular protein markers GAB1, β-catenin, filamin A, and YAP1 for the determination of defined molecular subgroups of medulloblastoma under in vitro conditions." (PMID 28231263, 2017). "SHH-activated medulloblastomas express specific target proteins such as p75NGFR and Gab1, share expression of nuclear Yap1 with the WNT medulloblastoma, but lack Otx2 expression." (PMID 27781424, 2016).